RNU1-112P (RNA, U1 small nuclear 112, pseudogene)
Gene: Small nuclear RNA gene on chromosome X (72,740,706 to 72,740,869, reverse strand). Ensembl gene ENSG00000201271.
Homologues: Orthologues: chimpanzee U1 (98% identical). Paralogues in human: RNU1-1 (80% identical), RNU1-2 (80% identical), RNU1-27P (80% identical), RNU1-28P (80% identical), RNU1-3 (80% identical), RNU1-4 (80% identical), RNU1-67P (80% identical), RNVU1-18 (80% identical), RNVU1-29 (80% identical), U1 (80% identical), RNVU1-28 (79% identical), RNVU1-7 (79% identical), and 134 more.